RN7SL824P (RNA, 7SL, cytoplasmic 824, pseudogene)
Gene: Miscellaneous RNA gene on chromosome 1 (92,402,389 to 92,402,685, reverse strand). Ensembl gene ENSG00000242764.
Homologues: Orthologues: chimpanzee Metazoa_SRP (94% identical), macaque Metazoa_SRP (92% identical), guinea pig Metazoa_SRP (62% identical). Paralogues in human: RN7SL2 (83% identical), RN7SL1 (83% identical), RN7SL3 (82% identical), RN7SL679P (81% identical), RN7SL408P (81% identical), RN7SL220P (80% identical), RN7SL296P (80% identical), RN7SL650P (80% identical), RN7SL788P (80% identical), RN7SL492P (80% identical), RN7SL493P (80% identical), RN7SL113P (79% identical), and 704 more.